OR56B2 (olfactory receptor family 56 subfamily B member 2)
Description:
Odorant receptor.
Synonyms: OR56B2P; OR11-63
Tractability: Antibody: UniProt places it where antibodies can reach, with high confidence; UniProt predicts a signal peptide or a membrane-spanning region; its Gene Ontology location is reachable by antibodies, with medium confidence.
Gene: Protein-coding gene on chromosome 11 (5,761,153 to 5,769,080, forward strand). Ensembl gene ENSG00000181017.
Subcellular location: Cell membrane
Gene Ontology:
Molecular function: olfactory receptor activity; G protein-coupled receptor activity; signaling receptor activity
Biological process: cellular response to lipid; detection of chemical stimulus involved in sensory perception of smell; G protein-coupled receptor signaling pathway; system process
Cellular component: plasma membrane; membrane
Homologues: Orthologues: dog OR56B2 (85% identical), rabbit OR56B2 (85% identical), dog OR56B2C (84% identical), rat Or56b2 (83% identical), dog OR56B2D (83% identical), mouse Or56b2 (81% identical), rat Or56b2b (80% identical), mouse Or56b2j (76% identical), tropical clawed frog or56c1 (43% identical). Paralogues in human: OR56B1 (72% identical), OR56B4 (66% identical), OR52L1 (40% identical), OR52E8 (40% identical), OR51L1 (40% identical), OR52K1 (39% identical), OR52K2 (39% identical), OR51A7 (38% identical), OR51E1 (38% identical), OR52B6 (38% identical), OR52E6 (38% identical), OR52D1 (38% identical), and 39 more.